MTOR (mechanistic target of rapamycin kinase)
Diseases named in the same sentence as MTOR in open-access papers (continued):
Sharing a sentence is not in itself a finding about the gene and the disease.
cancer (continued). "Given that the mTOR pathway is deregulated in a number of cancers, it was anticipated that mTOR inhibitors would have broad therapeutic application across many tumor types." (PMID 21834980, 2011). "mTOR signaling promotes cell proliferation, and, in the context of cancer development, it is highly correlated with tumor expansion and rate of tumor growth." (PMID 22145042, 2011). "Despite promising preclinical studies, targeting mTOR in cancer therapy has shown limited clinical benefits so far." (PMID 24212820, 2011). "THC, in a CB1-dependent fashion, stimulates mTOR in the hippocampus, but inhibits mTOR by stimulating ER stress in cancer cells." (PMID 22073164, 2011). "Leptin-mediated activation of mTOR, a pathway deregulated in many cancers, was involved in the regulation of IL-1 system." (PMID 21139583, 2011). "Specific Raf, MEK, PI3K, Akt, mTOR and Mdm-2 inhibitors have been developed and represent promising therapies for cancer and other proliferative diseases including premature aging." (PMID 21422497, 2011). "Until now, the effects of resveratrol and mTOR signaling on longevity and cancer have been considered independent, although mTOR signaling has been shown to be involved in both." (PMID 22242130, 2011). "There are several drugs in clinical development targeting all three, and a few drugs against mTOR that are currently approved for other cancer types." (PMID 21479172, 2011). "In summary, these studies show that ATP-competitive inhibitors of mTOR display a stronger antiproliferative effect than rapalogs and also frequently induce cancer cell apoptosis, which is rarely observed with rapalogs." (PMID 24212820, 2011). "The phosphoinositide 3-kinase (PI3K)-mammalian target of rapamycin (mTOR) signaling axis has emerged as a novel target for cancer therapy." (PMID 21695126, 2011). "Akt, mTOR and NF-κB are anti-apoptotic (prosurvival) signaling proteins that are constitutively active in a variety of human and animal cancers and provide survival advantage to cancer cells." (PMID 21961053, 2011). "Given that mTOR is the only one target of rapamycin, one can conclude that inhibition of mTOR is sufficient to suppress aging and delay cancer." (PMID 22267462, 2011). "mTOR plays a critical role in cell growth and tumorigenesis in different tumors, and its activation correlates with cancer progression, adverse prognosis and resistance to chemotherapy and molecularly-targeted therapies." (PMID 22203527, 2011). "Considering the strong connection between Akt and mTORC1 and the role of this signalling, frequently dysregulated in cancers, in the next section, we will focus our attention on the major component of the mTOR complex, the kinase mTOR." (PMID 21904669, 2011). "The mTOR pathway, which promotes cell proliferation, presents an attractive target for cancer therapy since it is deregulated in a wide range of cancer types and a large proportion of cases of each type." (PMID 21320304, 2011). "The mTOR pathway has been linked to cancer cell migration and our data support a model of signal cross-talk between CXCR4 and mTOR during cancer cell metastasis." (PMID 21949786, 2011). "Because of its critical role in promoting cell growth, mTOR is considered an attractive target in cancer." (PMID 21961653, 2011). "Based on these data, a combination of therapies directed against AMPK and the PI3K/AKT/mTOR pathways has emerged as an option for the treatment of cancer." (PMID 22203527, 2011). "Since the mTOR pathway is involved in cellular and organismal aging and age-related diseases, one can suggest that cancer preventive activities of “accidental” drugs are in part due to suppression of aging." (PMID 22267462, 2011). "Reversing these effects, and thereby reducing cell growth or inducing apoptosis, is thought to be the basis of the therapeutic action of mTOR inhibitors in cancer." (PMID 21320304, 2011).
cancer (continued). "GSIs have been shown to affect not only tumor cell growth via Notch, but also other targets e.g. erbB-4, mToR and Glut1 and thereby affecting other signaling pathways important for tumor growth, nutritional status of the tumor and possibly cancer stem cells." (PMID 21533193, 2011). "Since mTOR plays a central role in cell growth and proliferation and since it is frequently over activated in tumor cells, mTOR represents an ideal target in cancer therapy." (PMID 24212820, 2011). "During cancer development, the mTOR pathway is often abnormally up-regulated, which favours cancer cell survival, growth, replication, angiogenesis and metastasis." (PMID 21763421, 2011). "Recently the Ras/Raf/MEK/ERK and Ras/PI3K/PTEN/Akt/mTOR pathways have been shown to have roles in cancer stem cells, senescence, aging and sensitivity to targeted therapy." (PMID 21422497, 2011). "The direct, insulin-independent effects of metformin originate from LKB1-mediated activation of AMPK and a reduction in mTOR signaling and protein synthesis in cancer cells." (PMID 21470407, 2011). "As the mammalian target of rapamycin, mTOR was identified as a rapamycin substrate, and rapamycin was the first inhibitor tested against different human cancer cell lines." (PMID 24212653, 2011). "Of relevance to cancer therapy, mTOR inhibition also increases Mek/Erk signaling in endothelial cells." (PMID 24212820, 2011). "Clearly, a cancer cell would benefit greatly from hyperactive mTOR activity and this is what is observed in many forms of cancer." (PMID 21378410, 2011). "In our survey of the immune effects mediated by the combination of cancer vaccine and mTOR inhibition, temsirolimus had both immunosuppressive and immunostimulatory properties." (PMID 21285988, 2011). "Rapamycin targets two crucial signaling pathways involved in cell survival and chemoresistance of cancer cell, namely PI3k/Akt through mTOR and NF-κB through FKBP51." (PMID 22087835, 2011). "Activation of MAPK and mTOR makes cancer cells pro-senescent: it is sufficient to impose cycle arrest in order to reveal the senescent phenotype." (PMID 21297220, 2011). "The anti-tumour studies demonstrated that the net effect of immune modulation with mTOR inhibition was to enhance the cancer vaccine." (PMID 21285988, 2011). "Clinical trial data on safety and efficacy of dual mTOR inhibitors is emerging, particularly for the treatment of a variety of cancers." (PMID 22132311, 2011). "Loss of the PTEN tumor suppressor has been proposed to correlate with mTOR inhibitor sensitivity in some other cancer cell lines and patient tumors." (PMID 22039466, 2011). "mTOR is also another target of cancer therapy due to its central position in several pro-survival pathways (e.g., PI3K/Akt/mTOR)." (PMID 24212653, 2011). "Activation of growth factor receptors, Ras, Raf, PI3K, Akt, which all activate mTOR, are most common alterations in cancer." (PMID 22156391, 2011). "The PI3K, AKT, ERK, and mTOR prosurvival mediators are important therapeutic targets, as they are constitutively activated in many cancers and contribute to cancer progression by promoting cellular proliferation and inhibiting cell death signalling pathways." (PMID 21119656, 2011). "It is well-established that PI3K/Akt/mTOR pathways are activated in a variety of cancers, and these pathways are being explored as targets for therapeutic intervention of cancers." (PMID 21811619, 2011). "In vitro studies showed that inhibition of proliferation and induction of apoptosis in TRAMPC-1 cancer cells by CDDO-Me was associated with inhibition of p-Akt, p-mTOR and NF-κB." (PMID 21961053, 2011). "Akt, mTOR and NF-κB are major antiapoptotic signaling proteins that confer survival advantage and resistance of cancer cells to various forms of anticancer therapies." (PMID 21799944, 2010).
cancer (continued). "Not only does rapamycin inhibit tumour growth indirectly, cancer cells themselves are inhibited directly by their variable dependence on the mTOR pathway for cell growth and survival." (PMID 20459775, 2010). "In this review, we present the evidence which links the signals emanating from the PI3K/Akt/mTOR cascade with the functions of cancer stem cells, both in solid and hematological tumors." (PMID 24281174, 2010). "The potential anti-cancer effects of mammalian target of rapamycin (mTOR) inhibitors are being intensively studied." (PMID 20459775, 2010). "From a clinical perspective, mTOR inhibitors have begun to show efficacy with some types of cancer, including especially advanced renal cell carcinoma." (PMID 20459775, 2010). "It is hoped that with this added knowledge, the potential beneficial effects of inhibiting mTOR signaling in cancer patients will be fully recognized and realized in clinical practice." (PMID 21584218, 2010). "The resulting signals regulate Ras-mediated transformation, Raf-mediated gene expression changes, and akt/mTOR phosphorylating activity which are crucial for growth, survival, and migration of cancer cells." (PMID 20199686, 2010). "Signaling through the mTOR pathway contributes to growth, progression and chemoresistance of several cancers." (PMID 20543980, 2010). "This article highlights the current knowledge of mTOR biology and provides new insights into the role of mTOR in different cancers." (PMID 21584218, 2010). "The sensitivity of cancer cell lines to erlotinib depends at least partially on the inhibition of the PI3K/Akt/mTOR pathway." (PMID 20630061, 2010). "A deeper understanding of how mTORC1 controls cell cycle progression is essential for use of targeted mTOR inhibitors in the treatment of cancer and many other mTOR-related pathologies." (PMID 20169205, 2010). "Given that the mTOR pathway is deregulated in a number of cancers, it is anticipated that mTOR inhibitors will have broad therapeutic application across many tumor types." (PMID 21584218, 2010). "mTOR inhibition has also been shown to lead to MAPK activation through a PI3K-dependent feedback loop in human cancer." (PMID 21203579, 2010). "Recent cancer therapies include drugs that target both tumor growth and angiogenesis including mammalian target of rapamycin (mTOR) inhibitors." (PMID 20298531, 2010). "The understanding of the science behind mTOR’s role as a regulator of many cell processes and its potential as a therapeutic target has opened up treatment possibilities in several types of cancer." (PMID 21584218, 2010). "The PI3K/Akt/mTOR pathway is a survival pathway often constitutively activated in many types of cancer." (PMID 20653956, 2010). "Nevertheless, the extent to which disruption of negative feedbacks mechanism actually limits the therapeutic effects of mTOR inhibitors in cancer patients in vivo remains to be determined." (PMID 20671809, 2010). "Upstream in the growth-promoting pathways are critical molecules that converge on mTOR, which are often deregulated in some manner in cancer." (PMID 21584218, 2010). "It is possible that only a subset of cancer patients will have tumors sensitive to mTOR inhibitors as a monotherapy." (PMID 21584218, 2010). "In contrast, small molecules designed for inhibiting the catalytic site of mTOR, were much more effective in this respect, especially in cancer cells." (PMID 20671809, 2010). "PI3K/Akt/mTOR and Akt/NF-κB are major antiapoptotic/prosurvival signaling pathways that are frequently hyperactivated in many cancers." (PMID 21799944, 2010). "Translation rates are particularly robust in cancer cells, and deregulation of the PI3K/AKT/mTOR pathway was reported to contribute to cancer development and maintenance." (PMID 20539760, 2010).
cancer (continued). "This combination is interesting because it simultaneously inhibits two different molecules of the same signaling pathway (KIT-PDGFRA/PI3-K/AKT/mTOR) that impacts on cancer cell growth, survival, motility and metabolism." (PMID 21192792, 2010). "Mutated or down-regulated in many advanced cancers, PTEN loss activates the PI3K-AKT signaling pathway and its downstream target mTOR, with important implications in RCC development and therapeutic selection." (PMID 20420713, 2010). "Total lack or impairment of PTEN protein from cancer cells causes hyperactivation of the PI3K pathway, leading to uncontrolled function of several kinases, including the serine/threonine kinase mTOR (mammalian target of rapamycin)." (PMID 20148071, 2010). "Since mTOR plays a major role in cell growth and proliferation, targeting mTOR in cancer therapy has been viewed as a promising approach." (PMID 20226010, 2010). "Previous studies on mechanism underlying the regulation of autophagy in cancer cells showed that autophagy was regulated by multiple signaling pathways as diverse as the class III PI 3-kinase, and the protein kinases mTOR, ERK, and p38." (PMID 20808909, 2010). "Several mutations found in cancer produce inappropriate signals that activate the mTOR switch, driving the growth and proliferation of the cancer cell." (PMID 21584218, 2010). "Because of its essential role in cellular proliferation and frequent deregulation in cancer, mTOR has been intensively studied, leading to the use of rapamycin, a highly specific and potent mTORC1 inhibitor, in various forms of cancer." (PMID 21200439, 2010). "Rapamycin, an inhibitor of mTOR, was reported to induce the classic autophagic cell death in cancer cells." (PMID 20808909, 2010). "The established involvement of mTOR activity in the cellular processes that contribute to the development and progression of cancer has identified mTOR as a major link in tumorigenesis." (PMID 19860903, 2009). "Many of the key acquired capabilities of cancer cells can be affected by the inhibition of dysregulated mTOR activity, including cell cycle progression, cellular metabolism, cellular survival, and angiogenesis." (PMID 19860903, 2009). "mTOR signaling pathway and its downstream serine/threonine kinase p70S6k were frequently activated in human cancers." (PMID 20003385, 2009). "The eIF4E pathway is a target for cancer therapy with drugs that either inhibit eIF4E activity indirectly (mTOR inhibitors that reduce 4E-BP1 phosphorylation thereby inhibiting eIF4E), or directly (by binding to/reducing expression of eIF4E)." (PMID 19367274, 2009). "Combination of mTOR siRNA and rapamycin had also synergistic effect at inhibiting growth of several human cancer cell lines." (PMID 19457267, 2009). "Rapamycin and its derivatives, which specifically inhibit mTOR, induced rapid Akt (Ser473) phosphorylation both in cancer cells and in clinical patient tumors, presumably due to inhibition of a mTOR-dependent retrograde signal." (PMID 19293927, 2009). "Proteins in the PI3K/Akt/mTOR pathway that are dysregulated in cancer, such as PTEN, IGF-1/IGF-1R, and TSC, also contribute to RCC tumorigenesis." (PMID 19860903, 2009). "Deregulation of the phosphatidylinositol 3-kinases (PI3K)/Akt/mammalian target of rapamycin (mTOR) pathway plays a central role in tumor formation and progression, providing validated targets for cancer therapy." (PMID 19293927, 2009). "Mammalian target of rapamycin (mTOR) inhibitors such as everolimus are under intensive investigation for cancer therapy." (PMID 19436299, 2009). "The dysregulation of the mTOR pathway has been found to be a contributing factor of a variety of different cancer." (PMID 20003385, 2009).
cancer (continued). "Both the immunosuppressive and anti-cancer properties of sirolimus are due to the inhibition of the mammalian target of the sirolimus (mTOR) signalling pathway, which controls mRNA translation and induces angiogenesis and cell proliferation." (PMID 19128503, 2009). "The results of ongoing clinical trials with mTOR inhibitors, as single agents and in combination regimens, will better define their activity in cancer." (PMID 19860903, 2009). "Preclinical data have supported the pivotal role of mTOR in cancer and led to the development of mTOR inhibitors as a therapeutic target." (PMID 19860903, 2009). "The results of ongoing clinical trials with mTOR inhibitors, as single agents and in combination, will better define their activity in cancer." (PMID 19860903, 2009). "Inhibitors of mTOR are currently being tested clinically and have been somewhat disappointing as monotherapy against cancer." (PMID 19293927, 2009). "The mammalian target of rapamycin (mTOR) has received considerable attention as a possible target for cancer treatment." (PMID 19223902, 2009). "RAD001 has been shown to inhibit mTOR activity, thereby halting the proliferation of cancer cells, both in vitro and in vivo." (PMID 19128511, 2009). "This article will describe the normal functions of mTOR, its dysregulation in cancer, and its value as a target for inhibition by anticancer agents." (PMID 19860903, 2009). "The functional role of p70S6K1/2 in the PI3K/mTOR cascade has been well established in the vast majority of cancer and development research, and the role of p70S6K inhibition in suppressing PI3K pathway-activated cancers has been extensively studied." (PMID 19575820, 2009). "The importance of mTOR pathway in human pathology is reflected in the overexpression of p70S6K in a subset of cancer and its correlation with a poor prognosis." (PMID 19265534, 2009). "Univariate analysis indicated that expression of mTOR and nuclear p-P70S6K was closely linked to favorable prognosis of the carcinoma patients (p < 0.05)." (PMID 20003385, 2009). "The link between HIF-1 and EGF and the reported ability of mTOR inhibitors rapamycin and everolimus to reduce VEGF secretion in vitro and in vivo, renders mTOR inhibitors potentially effective against cancer cells resistant to EGFR inhibitors." (PMID 18319715, 2008). "This study was the first clinical trial showing a survival benefit in using an inhibitor of mTOR in patients with cancer." (PMID 18797463, 2008). "Several genes from the mTOR signaling pathway are known to be dysregulated in a wide spectrum of cancers." (PMID 18538015, 2008). "For example, PIK3CA, PTEN, TSC1/2, HER2, AKT, and PDPK1 have been found to be frequently mutated or amplified in cancer and thereby PI3K/AKT/mTOR pathway is an attractive target for therapeutics." (PMID 18652687, 2008). "EGFR is a major transducer of mitogenic signals involved in cancer pathogenesis and progression upstream of mTOR and an important target for anticancer therapy." (PMID 18319715, 2008). "Several components of the mTOR signaling pathway are known to be dysregulated in a wide spectrum of human cancers." (PMID 18538015, 2008). "The PI3K/AKT/mTOR signalling pathway has an important function in cancer cell survival in response to the insult induced by cytotoxic agents." (PMID 18797463, 2008). "The PI3K pathway was up-regulated in BLCs compared with HER2+ carcinomas as shown by a significant increased activation of downstream targets such as Akt and mTOR (mammalian target of rapamycin)." (PMID 19055754, 2008). "In vitro and in vivo studies of isogenic PTEN (+/+) and PTEN (-/-) mouse cells as well as human cancer cells with defined PTEN status confirmed that the growth of PTEN null cells was blocked preferentially by pharmacologic FRAP/mTOR inhibition." (PMID 19384426, 2007). "Inhibition of mTOR leads to G1 arrest of many malignant cell lines, and currently analogs of rapamycin are being investigated as cancer therapeutic agents." (PMID 17996122, 2007).